GPC1 (glypican 1)
Diseases named in the same sentence as GPC1 in open-access papers (continued):
Sharing a sentence is not in itself a finding about the gene and the disease.
colon cancer (6 papers, 2017 to 2025). "In a small group of colon cancer patients, elevated glypican-1 (GPC-1) was observed during the metastatic period." (PMID 36167539, 2022). "In this study, we addressed the role of GPC1 in prognosis and immune cell infiltration in colon cancer for the first time based on TCGA datasets." (PMID 36158119, 2022). "Here, we investigate the clinical significance of the concentrations of circulating GPC1 positive exosomes, miR-96-5p, and miR-149 in 85 patients with stage III colon cancer, as well as the biological function of GPC1 in colon cancer cells." (PMID 29254156, 2017). "To understand the clinical significance of GPC1+ plasma exosomes, miR-96-5p, and miR-149, we measured their abundance in colon cancer patients before and after surgery." (PMID 29254156, 2017). "The percentage of GPC1+ plasma exosomes one day before and one week after surgery was significantly higher in colon cancer patients with IIIC stage disease than that in patients with IIIA stage disease." (PMID 29254156, 2017). "The percentage of GPC1+ plasma exosomes progressively increased nine months after surgery in survived colon cancer patients with relapse." (PMID 29254156, 2017). "Further, our data suggest that Snail, by changing the level of GPC1 on EVs released by colon cancer cells, may affect the generation of a distant premetastatic niche and metastatic organotropism in colon adenocarcinoma." (PMID 32629890, 2020). "Our finding that GPC1 protein level was enhanced in EVs released from MC38 cells that were in an early EMT stage might explain, at least in part, the specificity of the GPC1 biomarker in colon cancer diagnosis." (PMID 32629890, 2020). "In addition, GPC1 found on patients exosomes as well as its regulative miRNAs are described as biomarkers in colon cancer." (PMID 32629890, 2020). "We conclude that a severe clinical status, poor prognosis, and relapse in stage III colon cancer patients can be suggested by observing high circulating GPC1 positive exosomes before and after surgery as well as low circulating miR-96-5p and miR-149 before surgery." (PMID 29254156, 2017). "Our results also show that a short overall survival time for colon cancer patients correlated with a high percentage of GPC1+ plasma exosomes one day before and one week after surgery, which suggests that the circulating GPC1+ exosomes are a marker for poor prognosis in colon cancer patients." (PMID 29254156, 2017). "We also found that a poor prognosis and relapse in stage III colon cancer patients could be predicted by the circulating GPC1+ exosomes, or the regulatory microRNA of GPC1 (miR-96-5p and miR-149)." (PMID 29254156, 2017). "Although the regulative effect of miR-96-5p and miR-149 on GPC1 gene expression was previously implicated in colon cancer cells, the direct targets of these micro RNAs have not yet been identified." (PMID 29254156, 2017). "Thus, the re-increase of circulating GPC1 positive exosomes in survived colon cancer patients with relapse may imply a re-population of tumor cells and formation of relapsed tumor mass locally or at a distal location." (PMID 29254156, 2017). "Glypican 1 (GPC1) is one of the most investigated surface markers of exosomes derived from pancreatic and colon cancer." (PMID 36109501, 2022). "This study first demonstrated that GPC1 can activate EMT and increase invasion and migration of colon cancer cells." (PMID 29254156, 2017). "Overexpression of GPC1 activated epithelial-mesenchymal transition (EMT) which then increased invasion and migration in HT29 and HCT-116 colon cancer cells." (PMID 29254156, 2017). "This study demonstrated that the percentage of GPC1+ plasma exosomes in total plasma exosomes measured one day before and one week after surgery was significantly higher in stage IIIC colon cancer patients than stage IIIA CRC patients." (PMID 29254156, 2017).
colon cancer (continued). "The percentage of GPC1+ plasma exosomes in total plasma exosomes one day before surgery and 9-24 months after surgery was significantly higher in survived colon cancer patients with relapse than in the patients without relapse." (PMID 29254156, 2017). "Our results indicate that high levels of circulating GPC1 positive exosomes before and after surgery as well as low circulating miR-96-5p and miR-149 before surgery indicated a severe clinical status and poor prognosis in stage III colon cancer patients." (PMID 29254156, 2017). "Our finding that GPC1 protein level was enhanced in EVs released from MC38 cells that overexpressed Snail and were in an early EMT stage might explain the specificity of the GPC1 biomarker in colon cancer diagnosis." (PMID 32629890, 2020). "Therefore, the upregulation of GPC1 protein expression in exosomes may be involved in the relapse of colon cancer patients through increasing EMT and subsequent enhancing invasion and migration of colon cancer cells." (PMID 29254156, 2017).
lymph node metastasis (6 papers, 2017 to 2025). "Another study reported a significant relation between GPC1 expression and tumor size and lymph node metastasis." (PMID 39797955, 2025). "With the increasing risk score of patients with lymph node metastasis of lung adenocarcinoma, the expression of high-risk mRNAs (HMMR, B4GALT1, ANGPTL4, EXT1, GPC1, RBCK1, SOD1, AGRN) was obviously upregulated." (PMID 31847905, 2019). "Preoperative serum exosomal and serum GPC-1 were not related to age, sex, CA19-9, location, tumor size, differentiation, nerve invasion, lymph node metastasis, or TNM stage." (PMID 36313694, 2022).
pancreatic adenocarcinoma (6 papers, 2017 to 2024). "The miR-1246 expression in GPC1 positive exosomes from 3 patients with localized pancreatic adenocarcinoma and 3 healthy donors were compared." (PMID 29100367, 2017). "As GPC1 was recently reported as a pancreatic adenocarcinoma exosome surface marker, we performed immunoaffinity isolation from whole plasma exosomes using the reported GPC1 antibody." (PMID 29100367, 2017). "According to the TCGA RNA sequencing data from pancreatic adenocarcinoma patients (n = 178), we observed that GPC1 is the major expressed form in pancreatic adenocarcinoma among the six glypican family members in the human genome (GPC1‐6)." (PMID 28440066, 2017). "A recent report demonstrated that GPC1 positive plasma exosomes are indicative of pancreatic adenocarcinoma in a large patient cohort study." (PMID 29100367, 2017). "Several studies have demonstrated that GPC1 is overexpressed in pancreatic adenocarcinoma." (PMID 39598037, 2024). "But the exosomal glypican 1 was positive in this sample, which may suggest a pancreatic adenocarcinoma." (PMID 35991837, 2022). "Whereas immunoaffinity isolation with the GPC1 antibody captured more exosomes from pancreatic adenocarcinoma patient plasma samples, miR-1246 expression in GPC1 positive exosomes is not elevated in patients with localized PDAC compared to the matched controls." (PMID 29100367, 2017). "To explore whether miRNAs in the GPC1 positive exosomes are better indicators of localized pancreatic adenocarcinoma, we utilized GPC1 antibody-conjugated beads to isolate GPC1 positive exosomes from the total plasma exosome populations." (PMID 29100367, 2017). "All pancreatic adenocarcinomas had positive exosomal glypican 1 while benign tumors were negative." (PMID 35991837, 2022). "However, plasma exosome miR-1246 expression levels in patients with localized pancreatic adenocarcinoma were not increased after GPC1 immunoaffinity isolation." (PMID 29100367, 2017).
biliary atresia (5 papers, 2017 to 2023). A rare, biliary tract disease characterized by progressive obliterative cholangiopathy of the intra- and extrahepatic bile ducts, occurring in the embryonic/ perinatal period, leading to severe and persistent neonatal jaundice and acholic stool. "Data has linked GPC1 with Shh in Biliary atresia and importantly identified GPC1 as a Shh receptor in commissural neurons." (PMID 30193893, 2019). "Other studies have demonstrated that mutations in FOXA2, GPC1, ADD3, PKD1L1, EFEMP1/3, STIP1, XPNPEP1, REV1 and JAG1 genes can increase an individual’s genetic susceptibility to biliary atresia." (PMID 37324459, 2023). "Other genes including FOXA2, GPC1, ADD3, PKD1L, EFEMP1/3, STIP1 were found to be associated with biliary atresia." (PMID 37324459, 2023). "Another study showed that GPC1 regulates hedgehog signaling in cholangiocyte in biliary atresia." (PMID 29245923, 2017).
breast tumor (5 papers, 2017 to 2025). "Several groups identified cell surface proteoglycan glypican-1 as a specific marker of circulating cancer-cell-derived exosomes in pancreas and breast tumors." (PMID 33330449, 2020). "Notably, collagen deregulation and ECM destabilization is a mechanism common in cancer fibrosis and GPC1 has been shown to directly interact with collagen in breast tumor growth regulation." (PMID 36944188, 2023). "α3(V) chains and GPC1 are shown to be separately expressed by basal and luminal cells, respectively, in normal mouse and human mammary gland, but to be coexpressed in luminal and basal-like human breast tumours, which may provide a ‘gain of autonomy' and thus growth advantage to tumour cells." (PMID 28102194, 2017). "Heparan sulfate proteoglycans (HSPGs) are abnormally expressed in BC tissues: GPC1 is overexpressed, while GPC3 and GCP5 show reduced expression, and GPC4 expression is downregulated in metastatic breast tumors compared with nonmetastatic breast tumors." (PMID 40443562, 2025).
colon adenocarcinoma (5 papers, 2020 to 2023). "GPC1 is overexpressed in colon adenocarcinoma and is associated with poor OS." (PMID 36158119, 2022). "We conducted bioinformatic analysis based on The Cancer Genome Atlas (TCGA) and used clinical samples to verify that GPC1 is overexpressed in colon adenocarcinoma." (PMID 36158119, 2022). "Nonetheless, there have been few systematic studies on GPC1 in colon adenocarcinoma (COAD)." (PMID 36158119, 2022). "Overexpression of Snail in MC38 colon adenocarcinoma cells induces EMT, and the Snail-overexpressing cells produce extracellular vesicles containing elevated quantities of GPC1." (PMID 36358747, 2022). "The pivotal role of GPC1 in EMT induction has been confirmed in several pathological conditions, such as esophageal carcinoma and colon adenocarcinoma." (PMID 36358747, 2022).
endothelial dysfunction (5 papers, 2022 to 2024). In vascular diseases, endothelial dysfunction is a systemic pathological state of the endothelium (the inner lining of blood vessels) and can be broadly defined as an imbalance between vasodilating and vasoconstricting substances produced by (or acting on) the endothelium. "In a mouse model of age-related vascular stiffness, endothelial dysfunction was associated with low glypican-1 levels and endothelial dysfunction." (PMID 39728298, 2024). "Furthermore, low levels of glypican-1 are found in a mouse model of age-mediated vascular stiffness and are associated with endothelial dysfunction." (PMID 35647072, 2022). "Gene silencing or overexpression of glypican 1 confirmed its protective role against stiffness-induced endothelial dysfunction." (PMID 39334952, 2024). "Knocking out glypican-1 in young mice results in a vascular phenotype typical of advanced age, characterized by arterial stiffness and endothelial dysfunction." (PMID 35647072, 2022). "When glypican-1 is shed, it leads to endothelial dysfunction, further complicating recovery." (PMID 39857617, 2024). "Glypican-1 shedding could be a potential target for alleviating endothelial dysfunction and improving clinical outcomes in cardiac surgery patients." (PMID 39857617, 2024). "This study examines how glypican-1 shedding, matrix metallopeptidase 9 (MMP9), and the pro-inflammatory cytokine IL-1β may contribute to endothelial dysfunction in patients undergoing on-pump surgery with an extended CPB." (PMID 39857617, 2024). "Older mice with naturally stiffer arteries showed reduced glypican 1 expression and more significant endothelial dysfunction, a condition exacerbated by glypican 1 deletion in young but not old knockout mice." (PMID 39334952, 2024).
lung carcinoma (5 papers, 2020 to 2024). "The relatively potent cytotoxicity of anti-GPC1 mAb in lung fibroblasts and its potential inhibitory effect on the paracrine FGFR signal transduction warrant further studies on the combined use of this mAb with targeted therapeutics to improve therapeutic outcomes in lung cancer." (PMID 38966167, 2024).
lung squamous cell carcinoma (5 papers, 2023 to 2026). "This study is to evaluate the value of immunohistochemical expression of glypican-1 in the diagnosis of lung squamous cell carcinoma (SCC)." (PMID 39797955, 2025). "GPC-1 expression was most significantly increased in lung squamous cell carcinoma (LUSC, P = 7.54e−130), Thymoma (THYM, P = 2.67e−81) and acute myeloid leukemia (LAML, P = 1.15e−58)." (PMID 38982153, 2024). "There is also a study that recommended the use of glypican-1 (GPC1) as an additional positive marker for lung squamous cell carcinoma." (PMID 37508851, 2023). "The calculated log2 transformed fold change of GPC1 mRNA levels indicated that GPC1 was up-regulated with 2.38-fold change in the squamous cell lung carcinoma biopsy specimens as compared with that in the paired normal lung tissues (adjusted P-value = 0.00399)." (PMID 38966167, 2024).
pancreatic diseases (5 papers, 2021 to 2025). "Another exosomal mRNA, glypican-1 (GPC1), provided excellent diagnostic performance in differentiating PaCa patients from patients with other pancreatic diseases and from healthy individuals, approaching 100% sensitivity and specificity." (PMID 34243775, 2021). "However, the molecular mechanisms of action underlying GPC-1 in pancreatic diseases need to be further explored." (PMID 36313694, 2022). "Detection of GPC1+crExos in the serum of PC patients has demonstrated high specificity and sensitivity for distinguishing non-neoplastic pancreatic diseases from early and advanced PC." (PMID 38720811, 2024). "However, a control population with pancreatic precancerous lesions was not tested in other studies evaluating GPC1+ EVs in pancreatic diseases." (PMID 36614326, 2023).
prostate tumor (5 papers, 2013 to 2021). "The ability of MIL-38-CD3 BiTE to mediate the activation of T cells in the presence of GPC-1-expressing prostate tumour cells was measured by flow cytometry analysis of the early activation marker CD69 and the late activation marker CD25." (PMID 33302918, 2020). "Of course, the use of primary prostate tumour cells in these in vitro assays would also be informative, particularly given the potential heterogeneity of GPC-1 expression in primary tumour." (PMID 33302918, 2020). "In prostate tumor tissues, a marked attenuation of total decorin and lumican expression was evident, whereas syndecan-1 and glypican-1 expression was increased in tumor stroma and attenuated in tumor epithelial cells." (PMID 32847060, 2020). "A striking dichotomy between data reported in this study and the literature is that GPC-1 expression is increased in prostate tumors and correlates to aggressiveness." (PMID 31391540, 2019). "This supports the hypothesis that GPC-1 acts as an inhibitor of prostate tumor growth, an observation supported by our recent in vivo studies." (PMID 33927256, 2021). "Interestingly, in normal prostate tissue, only epithelial cells expressed glypican-1, whereas prostate tumours displayed significant decrease of glypican-1 expression in cancer epithelial cells and an elevated glypican-1 levels in tumour stroma." (PMID 23691363, 2013). "In prostate tumours, complex changes in proteoglycans occur, with a common trend towards decrease of decorin and lumican expressions, and increase an overall expression of syndecan-1 and glypican-1, shifted from the epithelial cells to tumour stroma." (PMID 23691363, 2013). "Additionally, an aggrecan, syndecan-1, and glypican-1 expressions were detected in some prostate tumours." (PMID 23691363, 2013). "As a result, expression patterns for main proteoglycans in prostate tumours were highly individual with an ubiquitous expression for versican and tendency for the decreased decorin and lumican expressions and increased syndecan-1 and glypican-1 expressions in tumour tissues." (PMID 23691363, 2013). "While these data are among the first to report that inhibition of GPC-1 alters prostate tumor growth in vivo, they are not the first to suggest roles for GPC-1 in mediating tumor growth." (PMID 31391540, 2019). "In this study, expression of cell surface and stromal proteoglycans (glypican-1, perlecan, syndecan-1, aggrecan, versican, NG2, brevican, decorin, and lumican) in normal tissue and prostate tumours was determined by RT-PCR analysis and immunostaining with core protein- and GAG-specific antibodies." (PMID 23691363, 2013).
schizophrenia (5 papers, 2009 to 2021). A major psychotic disorder characterized by abnormalities in the perception or expression of reality. "We examined expression of known GPI-APs previously associated with schizophrenia, GPC1, NCAM1, MDGA2, and EPHA1." (PMID 30664618, 2019). "To investigate the potential consequences of a deficit in export and/or quality control, we measured cell membrane-associated expression of known GPI-APs that have been previously implicated in schizophrenia, including GPC1, NCAM, MDGA2, and EPHA1, using Triton X-114 phase separation." (PMID 30664618, 2019). "PI-PLC-sensitivity of GPI-APs between schizophrenia and comparison subjects was also determined, with GPC1 [t = 2.19, p = 0.046] and NCAM [t = 2.57, p = 0.022] having decreased sensitivity to PI-PLC treatment in schizophrenia." (PMID 30664618, 2019). "We observed decreased sensitivity of DT phase-associated GPC1 and NCAM1, suggesting decreased expression of membrane-bound GPI-anchored GPC1 and NCAM1 in schizophrenia." (PMID 30664618, 2019). "They identified GPC1 as a candidate risk factor for schizophrenia and proposed a model, in which epistatic interactions between GPC1 and FGF17 during brain development are involved in the etiology of schizophrenia." (PMID 33679334, 2021).
atherosclerosis (4 papers, 2023 to 2025). A disease characterized by the build-up of fatty material and calcium deposition in the arterial wall resulting in partial or complete occlusion of the arterial lumen. "First, Gpc1‐encoded phosphatidylinositol proteoglycan is associated with fluid shear stress, atherosclerosis and proteoglycans in cancer, highlighting its significant role in vascular and tumour biology." (PMID 41230834, 2025). "Gpc1 was linked to pathways related to fluid shear stress and atherosclerosis as well as proteoglycans in cancer." (PMID 41230834, 2025). "GPC1 is present in endothelial cells throughout the body as a glycocalyx that protects normal tissues, and previous reports have shown that GPC1 expression is suppressed by atherosclerosis." (PMID 39300946, 2024). "Glypican-1 was identified in the vein and lymphatic GCX, correlating with previous reports regarding its function in endothelial homeostasis and its anti-atherosclerosis properties." (PMID 36810649, 2023). "In ECs, expression of various HS-proteoglycans is known, including SDC1, 2, 4, and GPC1, 3, 4, but their role in atherosclerosis has not been adequately described thus far." (PMID 37511353, 2023).